LRG1 (leucine rich alpha-2-glycoprotein 1)
Diseases named in the same sentence as LRG1 in open-access papers (continued):
Sharing a sentence is not in itself a finding about the gene and the disease.
Sepsis (continued). "Our microarray analyses showed that LRG1 mRNA levels are higher in patients with sepsis." (PMID 33132754, 2020). "In addition, the diagnostic value of LRG1 for sepsis was not fully investigated, and additional research is necessary to further understand the diagnostic significance of LRG1." (PMID 34675320, 2021). "For ELISA validation, six proteins were selected (SAA-1, LRG1, PSMB1, sCD300a, sCD300b, and sCD25) in a larger cohort (21 healthy donors, 37 sepsis/septic shock patients and 15 HLH patients)." (PMID 41463121, 2025). "Compared to the controls, the patients with sepsis consistently showed significant isoform switching of the FLOT2, LRG1 and MEGF9 genes." (PMID 35715539, 2022). "There are remarkable differences in ANKRD22, GPR84, GYG1, BLOC1S1, CARD11, NOG, and LRG1 gene expression and enriched pathways among different molecular subgroups of sepsis, which may be the key factors leading to the heterogeneity of clinical symptoms and prognosis in patients with sepsis." (PMID 36035194, 2022). "However, the role of LRG1 in sepsis remains unclear to the best of our knowledge." (PMID 33132754, 2020). "According to our results, the serum concentration of SAA-1 and LRG1 could contribute to the differential diagnosis between HLH and sepsis." (PMID 41463121, 2025). "In line with the expression patterns, ROC curve analyses for the differential diagnosis between HLH and sepsis yielded excellent AUC values for PSMB1 (0.98) and very good values for SAA-1 and LRG1 (>0.8), indicating superb discriminatory performance in our cohort." (PMID 41463121, 2025). "Thus, SAA-1 and LRG1 showed very good discrimination between HLH and sepsis, whereas PSMB1 displayed excellent discriminatory performance in this dataset." (PMID 41463121, 2025). "Three proteins, including carbonic anhydrase 1 (CA1) and leucine-rich α -2-glycoprotein (LRG1), were identified in all samples from patients with sepsis compared with those without sepsis." (PMID 35874763, 2022). "Nine differentially expressed proteins that might be related to sepsis and SIRS were tested further by ELISA, and CRP, LRG1, and SAA were chosen as the target biomarkers." (PMID 34675320, 2021). "Ten genes included LRG1 were differentially expressed in sepsis compared with nonsepsis blood." (PMID 35095520, 2021).
heart failure (16 papers, 2012 to 2024). Inability of the heart to pump blood at an adequate rate to meet tissue metabolic requirements. "Several studies show that elevated levels of LRG1 are associated with a wide range of diseases, including cancer, heart failure, and inflammatory diseases." (PMID 39595649, 2024). "Another study identifies that elevated LRG1 is independently linked with increased occurrence of heart failure in type 2 diabetes patients." (PMID 38742172, 2024). "A reduced expression of LRG1 is associated with cardiac remodelling characterised by hypertrophy, fibrosis, and abnormal vasculature in various conditions leading to heart failure." (PMID 28509980, 2015). "Understanding the molecular mechanism underlying the role of LRG1 and its regulation in cardiac remodelling process will assist the development of novel treatments for heart failure." (PMID 28509980, 2015). "Further prospective studies with larger cohorts of patients at varying stages of asymptomatic DD and symptomatic heart failure, as well as healthy controls, are warranted to validate the clinical utility of LRG1 as a novel biomarker for risk stratification and prognostic evaluation." (PMID 36979923, 2023). "Previous studies have noted a close association between LRG1 and cardiovascular disease, demonstrating that increased levels of circulating LRG1 were associated with increased risks for coronary artery disease, heart failure, and mortality." (PMID 37916147, 2023). "Although a great deal of work is still needed to fully understand the underlying mechanisms, targeting LRG1 and its regulators might offer a unique approach to treating heart failure by simultaneously targeting different pathologies of the disease." (PMID 28509980, 2015). "Other studies reported a positive correlation between circulating or coronary sinus LRG1 levels and the incidence of heart failure and idiopathic pulmonary arterial hypertension." (PMID 35062948, 2022). "Since LRG1 has long been considered a promising biomarker for various pathologies, including inflammation, neurodegenerative disease, heart failure, and several types of cancer, further studies should investigate other roles of LRG1 in these diseases." (PMID 35562586, 2022). "The potential relevance of LRG1 in cardiac fibrosis has recently been suggested in a mice experimental model of chronic pressure overload-induced heart failure." (PMID 35216460, 2022). "Uncovering potential lncRNAs and mRNAs, including LRG1 was essential biomarkers from acute myocardial infarction aggravated to heart failure." (PMID 35095520, 2021). "Further studies are required to evaluate the efficacy and toxicity of LRG1 treatment for heart failure." (PMID 28509980, 2015). "This review will focus on the interaction between LRG1 and TGFβ signalling, their involvement in the pathogenesis of heart failure, and the potential for LRG1 to function as a novel therapeutic target." (PMID 28509980, 2015). "In this review, we summarise the current knowledge on the role of TGFβ1 and its novel modulator, LRG1, in different pathologies of cardiac remodelling and the potential of LRG1-targeted therapeutics for the treatment of heart failure." (PMID 28509980, 2015). "Despite different aetiologies, a decreased Lrg1 expression is associated with deterioration of cardiac function with lowest Lrg1 expression observed at the advanced stage of heart failure in both mouse models (GDS411 / aa172851_s_at / Lrg1)." (PMID 28509980, 2015). "Another proteomic analysis revealed that LRG1 may be a potential biomarker for early diagnosis of heart failure." (PMID 38742172, 2024). "In view of the beneficial effects that LRG1 exerts on tissue repair, it has been suggested as a novel compound for the treatment of chronic wounds and heart failure, although animal studies are still required to corroborate these findings and to assess the safety and toxicity of such approaches." (PMID 35062948, 2022).
heart failure (continued). "Plasma LRG1 might potentially be involved in the pathogenesis of heart failure in type 2 diabetes patiens." (PMID 35095520, 2021). "LRG1 overexpression in myocardium might restore cardiac function and slow down the progression of heart failure in both models." (PMID 28509980, 2015). "LRG1 was identified as a serum biomarker that identifies patients with heart failure." (PMID 23101585, 2012). "In patients with different types of heart failure, high LRG1 level consistently identified patients with high brain natriuretic peptide (BNP) levels and can even identify heart failure independently from BNP33." (PMID 32249825, 2020). "LRG1 might be a potential serum biomarker for early onset myocardial infarction, while a combined biomarker signature that included BNP (plasma brain natriuretic peptide) would be a more accurate predictor of heart failure than BNP alone." (PMID 35095520, 2021). "He found that LRG1 was consistently overexpressed in high BNP serum and identified heart failure patients independent of BNP." (PMID 36979923, 2023).
autoimmune disease (15 papers, 2016 to 2025). A disorder resulting from loss of function or tissue destruction of an organ or multiple organs, arising from humoral or cellular immune responses of the individual to their own tissue constituents. "LRG-1 has been proven to be associated with inflammation and autoimmune disease in the past few years." (PMID 30760292, 2019). "Moreover, other autoimmune diseases, such as Behcet′s disease (BD) and Crohn′s disease (CD), are also associated with increased LRG1 expression." (PMID 28505104, 2017). "LRG1 is also dysregulated in several autoimmune diseases, such as psoriasis, lupus nephritis, vasculitis, and RA." (PMID 40665055, 2025). "In line with this, increased LRG1 has been observed in various inflammatory and autoimmune diseases." (PMID 34930899, 2021). "Increased leucine-rich α2-glycoprotein-1 (LRG1) has been observed in various inflammatory and autoimmune diseases." (PMID 32252660, 2020). "Emerging evidence demonstrated that plasma LRG1 serves as a serum biomarker for various inflammatory and autoimmune diseases." (PMID 32249825, 2020). "LRG1 has also been shown to be correlated with disease severity indexes in autoimmune diseases." (PMID 40665055, 2025). "LRG1 has been shown to be aberrantly expressed in several autoimmune diseases." (PMID 40665055, 2025). "Understanding LRG1 activity in endothelial activation might provide a new avenue for therapeutic discovery in inflammatory and autoimmune diseases." (PMID 34291056, 2021). "LRG1 was reported to be involved in inflammatory and autoimmune diseases." (PMID 32252660, 2020). "Unlike RA and ulcerative colitis, patients with allergic airway disorders possess a feature of decreased LRG1 concentration in their plasma, which may serve as a maker to differentiate allergic disease from autoimmune disease." (PMID 27378305, 2016). "In light of the role of LRG1 in TNFR1 shedding, the potential therapeutic role of LRG1 in inflammatory and autoimmune diseases, including in atherosclerosis, should be investigated further." (PMID 34291056, 2021).
ulcerative colitis (15 papers, 2016 to 2025). An inflammatory bowel disease involving the mucosal surface of the large intestine and rectum. "For example, serum LRG1 is positively correlated with both clinical activity and endoscopic activity in ulcerative colitis patients; it is also positively associated with CRP level, ferritin level, and disease activity in systemic juvenile idiopathic arthritis patients." (PMID 40665055, 2025). "For example, serum LRG1 level was elevated in psoriasis patients and psoriatic arthritis patients compared to health controls; serum LRG1 level was also increased in ulcerative colitis patients compared with health controls." (PMID 40665055, 2025). "Recently, LRG1 has been recognized as a proinflammatory marker and found to be elevated in patients with ulcerative colitis, type 1 diabetes or RA." (PMID 33013889, 2020). "LRG1 influences epithelial repair in patients with ulcerative colitis." (PMID 38656694, 2024). "Interestingly, elevated serum levels of both adiponectin and LRG1 have been found in patients with ulcerative colitis, an inflammatory bowel disease usually affecting the colon and rectum." (PMID 36739457, 2023). "In ulcerative colitis, LRG1 level is elevated and parallel to disease activity." (PMID 32249825, 2020). "For example, LRG1 the most markedly altered gene in Rorc-/- x TRAG mucosa, is a signature serum marker for active ulcerative colitis and mucosal healing." (PMID 38512959, 2024).
inflammatory bowel disease (14 papers, 2021 to 2025). A spectrum of small and large bowel inflammatory diseases of unknown etiology. "Recent studies have also shown its association with inflammatory bowel disease and suggest LRG1 as a useful biomarker of endoscopic disease activity during treatment." (PMID 39595649, 2024). "Elevated serum LRG1 levels are associated with various diseases, including different types of cancer, inflammatory bowel disease, joint disorders, and cardiovascular diseases." (PMID 34291056, 2021). "LRG1 was recently reported as a biomarker for the activity of inflammatory bowel disease." (PMID 34499692, 2021).
Obesity (14 papers, 2015 to 2025). Accumulation of substantial excess body fat. "Projected upregulations were observed in the adipokine LRG1 (Leucine-rich alpha-2-glycoprotein 1) associated with liver diseases, notably in obesity-induced hepatosteatosis and insulin resistance." (PMID 38719902, 2024). "cDIP also displays some similarity (33% identical, 23% similar amino acids) to Leucine-rich alpha-2-glycoprotein 1 (LRG1) a secreted obesity-linked cytokine that regulates insulin signaling." (PMID 39483909, 2024). "One of the strengths of our study is that it is one of the first studies to explore the association between LRG1 and obesity in adolescents as the majority of the previous studies were carried out on adults." (PMID 35955698, 2022). "Recently, whole-body LRG1 loss of function has been reported to reduce obesity and improve insulin sensitivity by reduction of hepatosteatosis." (PMID 36346018, 2022). "Taken together, these results suggest that LRG1 overexpression attenuated pro-inflammatory processes associated with obesity." (PMID 36346018, 2022). "Recently, whole-body LRG1 loss of function has been reported to reduce obesity and improve metabolic health by reducing hepatosteatosis." (PMID 36346018, 2022). "In this study, we investigated the association of LRG1 with obesity markers, including leptin and other adipokines in adolescents (11–14 years; n = 425)." (PMID 35955698, 2022). "High concentrations of LRG1 are closely linked to obesity and might serve as an early obesity marker in overweight adolescents." (PMID 39595649, 2024). "Along with this, LRG1 has been associated with obesity in adolescence." (PMID 37148275, 2023). "Another study showed that obesity-associated adipokine leucine-rich alpha-2-glycoprotein 1 (LRG1) bound with high selectivity to the liver and exacerbated high fat diet-induced hepatosteatosis and IR by increasing de novo lipogenesis and suppressing fatty acid β-oxidation." (PMID 35692404, 2022). "AAV-mediated LRG1 overexpression in the adipose tissues led to a constellation of metabolic effects in both B6 and db/db mice, resulting in improvement of glucose/insulin tolerance as well as a reduction of obesity-associated inflammation." (PMID 36346018, 2022). "Additionally, we assessed the association between LRG1 and several obesity markers, including HsCRP, chemerin, and leptin." (PMID 35955698, 2022). "Therefore, we plan to perform a longitudinal study to further explore the role of LRG1 in the development of obesity and the mechanism of its association with these inflammatory markers." (PMID 35955698, 2022). "The consistent positive association between LRG1 and obesity reported in diverse studies from various ethnic groups suggests that LRG1 could be used as a universal obesity marker." (PMID 35955698, 2022). "Therefore, it was crucial to investigate the association between LRG1 and several obesity markers and to compare LRG1 levels between obese, overweight, and normal-weight adolescents." (PMID 35955698, 2022). "We investigated the association between LRG1 levels and obesity and CVD risk factors." (PMID 35955698, 2022). "In conclusion, higher plasma LRG1 levels were observed in obese and overweight adolescents compared with their normal-weight counterparts, indicating that LRG1 was associated with increased obesity risk." (PMID 35955698, 2022). "Since recent studies revealed that LRG1 is also secreted by adipocytes, it has been studied in the context of adipose tissue and obesity." (PMID 39595649, 2024). "Our findings agree with several published reports showing that LRG1 correlates positively with obesity." (PMID 35955698, 2022). "While endogenous LRG1 levels increase with obesity, further induction of LRG1 expression via AAV transduction protected mice from obesity-related complications." (PMID 36346018, 2022). "With iWAT expansion in obesity, this induction likely contributes to elevated serum LRG1 levels in this state." (PMID 36346018, 2022).
Obesity (continued). "We demonstrate, using two types of viral vectors and two different mouse models of obesity, a novel metabolic role for adipose-derived LRG1 as a regulator of glucose homeostasis by promoting insulin sensitization." (PMID 36346018, 2022). "The pro-inflammatory setting of obesity also induces LRG1 in other adipocytes, and this increase in circulating LRG1 modulates inflammation by directly binding Cyt c." (PMID 36346018, 2022). "Taken together, these observations suggest that LRG1 overexpression prevents obesity-related dysregulation of glucose homeostasis by insulin sensitization." (PMID 36346018, 2022). "We here describe a metabolic role for leucine-rich α–2 glycoprotein 1 (LRG1) as an obesity-regulated adipokine secreted by mature adipocytes." (PMID 36346018, 2022). "As inflammation is a key mechanistic link between obesity and insulin resistance, these findings strongly suggest LRG1 promotes insulin sensitization via modulation of inflammation and cell death during adipose tissue remodeling." (PMID 36346018, 2022). "The correlation between LRG1 and BMI could be explained by the relationship of LRG1 with thyroid hormones, insulin, angiogenesis, and obesity-related markers." (PMID 40665055, 2025). "Taken together, these results demonstrate that LRG1 is an obesity-induced adipokine." (PMID 36346018, 2022). "Moreover, a positive correlation was observed between LRG1 and other obesity markers, including HsCRP, leptin, and chemerin." (PMID 35955698, 2022). "Our observations indicate that LRG1 and HsCRP might be part of a common pathway involved in the development of obesity as they both show a significant positive correlation with obesity." (PMID 35955698, 2022). "LRG1 is secreted by mature adipocytes and increased in obesity." (PMID 36346018, 2022). "LRG1 or targeting extracellular Cyt c could be an attractive therapeutic approach for treatment of not only obesity but a variety of inflammatory conditions." (PMID 36346018, 2022). "Additionally, elevated levels of LRG1 were observed in fat depots of adults with obesity and positively correlated with waist circumference and body mass index (BMI)." (PMID 35955698, 2022). "Lastly, our findings suggest that LRG1, chemerin, leptin, and HsCRP might be part of a common pathway involved in the development of obesity, possibly through P38/MAPK signaling pathway." (PMID 35955698, 2022). "These similar findings indicate that ethnicity might not be involved in the association between LRG1 and obesity as the other studies were carried out on Caucasian and Asian participants while our study subjects were Arabs." (PMID 35955698, 2022). "This, together with the observation that circulating LRG1 preferably binds to hepatocytes, supports the hypothesis of LRG1 being a novel adipokine orchestrating an almost exclusive metabolic crosstalk between adipose tissue and liver in obesity." (PMID 35062948, 2022). "Suppressing the expression and function of either LRG1 or HPX presents a promising strategy for combating obesity and obesity-related metabolic diseases." (PMID 39339686, 2024). "LRG1 and HPX were among the twenty-three up-regulated proteins in the generational obesity comparison group." (PMID 39339686, 2024). "Interestingly, high levels of CRP are positively correlated with an increase in LRG1 and HPX, suggesting the potential interplay between these proteins in the context of obesity." (PMID 39339686, 2024). "Because LRG1 overexpression in B6 animals mitigated hyperglycemia, we explored whether LRG1 can improve glucose homeostasis in C57BLKS/J-Leprdb/db (db/db) mice, a more extreme model of obesity-related type 2 diabetes." (PMID 36346018, 2022). "Our findings also suggest that LRG1 might be an early obesity marker as the difference in LRG1 levels between overweight and obese groups was not significant." (PMID 35955698, 2022).